CLDN5 (claudin 5)
Diseases named in the same sentence as CLDN5 in open-access papers (continued):
Sharing a sentence is not in itself a finding about the gene and the disease.
tumor (continued). "The intestinal and tumor microbiome influences BBB permeability, and in the absence of normal intestinal flora, BBB permeability is significantly higher, which is the result of reduced expression of the tight junction proteins occludin and claudin-5." (PMID 39940760, 2025). "Similarly, the levels of the tight junction molecules claudin-5 and zonula occludens-1 (ZO1) were also significantly decreased in CD93–/– tumor vessels as compared with the wild-type group." (PMID 38441970, 2024). "Further quantification of the area fraction ratio of protein over blood vessel (CD31) suggested that the relative protein coverage ratio for Claudin-5, VE-Cadherin, Occludin, and JAM-A was comparable at the tumor core, margin, and contralateral side during 7–21 dpi." (PMID 37582846, 2023). "A total of 3842 endothelial cells from seven tumor samples and one paracancerous tissue were obtained from the GEO database, based on the marker genes VWF, CDH5, RAMP2 and CLDN5,26, 27 of which 3724 and 118 cells were derived from cancer tissues and paracancerous tissue, respectively." (PMID 37726969, 2023). "In comparison, icSFT/HPCs displayed occasional foci with tumor vasculature that were negative for CLDN5 but strongly positive for CD34." (PMID 33799999, 2021). "Since this is a descriptive study, further clinical investigations are needed to determine whether claudin-5 is correlated with development and progression of cutaneous SCC in EV patients, which could allow its use as a tumor biomarker." (PMID 32518268, 2020). "Since we observed claudin-5 upregulation from EV flat warts to cSCC samples, it is plausible to hypothesize that beta-HPV might act at an initial stage of skin carcinogenesis, but the mechanism by which beta-HPV changes claudin expression is still unclear." (PMID 32518268, 2020). "In our analyses of structural changes of blood vessels in the tumor core region, we found that Thal dose-dependently increased α-SMA+ pericyte coverage, distribution of endothelial junctional molecules Claudin-5 and VE-cadherin on tumor vessels compared with control." (PMID 31656203, 2019). "Tumour cells arrested preferentially in vascular branching points and left the junctions intact in the first 4 days, as assessed by PECAM-1 (platelet and endothelial cell adhesion molecule) and claudin-5 immunostainig and TEM." (PMID 31426859, 2019). "In MCT998G, there was also an increase in claudin-5 mRNA, a transmembrane protein that can regulate the paracellular permeability of small molecules, which appears not to be negatively regulated in most tumor microvessels." (PMID 40284027, 2025). "Again, in GBM regions with hyperintense FLAIR signal that did not enhance on Gd-MR, the BBB of vessels surrounded by tumor cells was not disrupted, as demonstrated by the continuous ZO-1 immunoreaction of Glut-1 positive vessels and by Claudin-5 expression of lectin-positive vessels." (PMID 31861603, 2019). "We concluded that combined modulation of Wnt/Dkk-3/claudin-5 and TLR-4 pathways, simultaneously targeting apoptosis and survival signaling defects, might shift the balance from tumor growth stasis to cytotoxic therapeutic responses, flowing in greater therapeutic benefits." (PMID 30680070, 2018). "For example, during the process of tumor-mediated angiogenesis, BM recruit healthy endothelial cells from surrounding brain parenchyma, but the vascularization process is disturbed by tumor-induced lack of transmembrane tight junction proteins occludin, claudin-1, and claudin-5." (PMID 28493907, 2017). "Although the underlying mechanism responsible for increased MRT-induced tumor BBB permeability is not yet clear, conventional radiation has been associated with the decreased expression and rearrangement of TJ proteins including claudin-5, ZO-1 and beta-catenin." (PMID 33198244, 2020).
tumor (continued). "A combination of western blotting and immunochemistry analysis also demonstrated that papaverine could downregulate claudin-5, occludin and F-actin expression by tumor microvessels, but not in normal brain tissue, suggesting that the tumor BBB opening was due to TJ dysfunction." (PMID 33198244, 2020). "Furthermore, we demonstrated, for the first time, an interesting TLR-4/Wnt modulation, suggesting that combined therapies that simultaneously enhance Wnt/Dkk-3/claudin-5 activity and inhibit TLR-4 pathway, might shift the balance from tumor growth stasis to cytotoxic therapeutic responses." (PMID 30680070, 2018). "Consistent with the immunofluorescence observations, we found that conditioned medium from tumor cells with MSLN knockdown did not induce as much degradation of the cadherin, JAM-A and claudin-5 expression patterns among hBMVEC monolayers." (PMID 38570866, 2024). "Using the TIMER database, we detected a negative correlation between the mRNA level expression of CLDN5, CLDN8, CLDN11, and CLDN18 and CRC tumor purity." (PMID 35281827, 2022).
infection (59 papers, 2010 to 2025). The state of being infected such as from the introduction of a foreign agent such as serum, vaccine, antigenic substance or organism. "Three days after infection with influenza A, mice were injected intravenously with microbubbles bound to a plasmid encoding human claudin-5 followed immediately by treatment with thoracic ultrasound." (PMID 37310768, 2023). "In an attempt to characterize the mechanisms underlying A. cantonensis-induced blood-CSF barrier dysfunction, we investigated the association of NF-κB, MMP-9 and claudin-5 in the choroid plexus of the mouse brain after infection with A. cantonensis." (PMID 23505411, 2013). "Functionally, there are patchy deficiencies in vascular barrier integrity following infection, with a spatial distribution that closely matches the clustering of CLDN5 and PECAM1, as revealed by extravasation of Sulfo-NHS-biotin, a low molecular weight intravascular tracer." (PMID 37318981, 2023). "MMP-9 could cause claudin-5 degradation and promote leukocyte infiltration into CSF via the paracellular route during infection with A. cantonensis in mouse choroid plexus." (PMID 23505411, 2013). "Infection of the pulmonary endothelium can lead to endothelial apoptosis and microvascular leak; furthermore, even replication-deficient virus can promote the loss of claudin-5, a critical component of endothelial tight junctions." (PMID 23115643, 2012). "In cells with normal expression of the Bmal1 gene, infection with ZIKV at 2 dpi significantly decreased claudin-5 mRNA levels." (PMID 40313764, 2025). "An increase in CLDN5 expression 6 weeks after infection, indicates a recovery of the gut, primarily restoring pore formation and stability." (PMID 40446677, 2025). "MA10 infection resulted in six additional down-regulated (Cpe, B2m, Pltp, Sparc, Cldn5, Vtn) and four up-regulated DEGs (Slc2a1, Vim, Apod, Acta2), whereas Aβ pathology alone produced one down-regulated (Slc2a1) and three upregulated DEGs (Gfap, Psen1, Clu)." (PMID 41497643, 2025). "At 72 hours post-infection, there was a significant decrease in mRNA transcription levels of TJ proteins (Tight Junction Protein 1, occludins, and claudin-5) compared to control cells." (PMID 40584180, 2025). "Infection led to a significant reduction in claudin-5 fluorescence intensity in WT and FPR2-KO mice (**** p < 0.0001; two-way ANOVA followed by the Bonferroni test)." (PMID 39768195, 2024). "We compared the regulation of Egr-1 on the TJ proteins, including ZO-1, Occludin, and Claudin-5 in both Egr-1−/− and WT hBMEC in response to the infection." (PMID 38233877, 2024). "The reduction in claudin-5 fluorescence intensity at 48 h post-infection and in the mortality group was significant (** p < 0.01, *** p < 0.001; one-way ANOVA followed by Bonferroni test)." (PMID 39768195, 2024). "The results showed that GPS infection significantly decreased the expression of ZO-1 (p < 0.05), Occludin (p < 0.01), and Claudin-5 (p < 0.05) in the mouse cerebrum." (PMID 38927100, 2024). "For example, while claudin-5 mRNA levels started to decline at early time points (within 24 h) post-infection, VE-cadherin decreased most significantly during the late stage (days) after infection." (PMID 37245027, 2023). "In leptomeninges flatmounts, infection produces mislocalization and clustering of CLDN5 and PECAM1, disorganized capillary morphology, and an expansion of the area covered by capillaries." (PMID 37318981, 2023). "Claudin-5 mRNA levels decreased at earlier time points (24-h) after infection while occludin mRNA levels remained unchanged." (PMID 37245027, 2023). "Claudin-5 mRNA levels decreased at earlier time points (24-hours) after infection while occludin mRNA levels remained unchanged." (PMID 36778380, 2023). "In response to infection, the leptomeningeal vasculature of Tlr4-/- mice showed minimal changes in the distribution of CLDN5 and very few regions of Sulfo-NHS-biotin leakage." (PMID 37318981, 2023).
infection (continued). "The WB results showed the expression level of those proteins, including VE-cadherin, claudin-5, and occludin in infected hCMEC/D3 cells were significantly lower at 48 h post-infection with viral dose dependence compared to the mock group." (PMID 37773164, 2023). "For example, while claudin-5 levels started to decline early (within 24 hours) post-infection, VE-cadherin decreased most significantly during the late stage (days) after infection." (PMID 36778380, 2023). "We next investigated the endothelial cell gene expression of tight junction proteins (ZO-1, JAM-A, Occludin and Claudin-5) and adherens junction protein (VE-Cadherin) in response to 2, 4 or 6 days of infection with SARS-CoV-2." (PMID 37537664, 2023). "We found the mRNA transcription levels of TJP1, OCLN, and CLDN5 were unaffected by the infection at 24 h, but were significantly decreased after 72 h of SARS-CoV-2 infection." (PMID 35705998, 2022). "To observe T. gondii motility in the brain during infection, we imaged the parasites in Tie2::eGFP-claudin-5 reporter mice." (PMID 36445695, 2022). "After infection with C. jejuni, HT-29/B6 cell monolayers showed a redistribution of barrier-maintaining occludin and claudin-5 off the TJ domain into intracellular compartments of the epithelial cells." (PMID 33935732, 2021). "APEC XM and APEC ΔclbH/pclbH infection resulted in a significant decrease in ZO-1, occludin, and claudin-5 protein expression compared to that in the control group (p < 0.01)." (PMID 34529552, 2021). "After infection with C. jejuni the TJ proteins, occludin and claudin-5 were redistributed off the TJ domain of the epithelial cells." (PMID 33935732, 2021). "Similar to this, we previously observed a subcellular redistribution of the TJ proteins occludin, claudin-4 and claudin-5 as well as a disorganization of E-cadherin and F-actin in colonic mucosae from pigs infected with E. coli 536 at 5 h after infection." (PMID 34437391, 2021). "Immunoblotting analysis showed that occludin and claudin 5 were downregulated 36 h and 24 h after infection, respectively." (PMID 32038167, 2020). "We observed a striking effect on tight junctions, labeled by claudin-5, as early as 2 days post-infection, with increasing disruption by 4 days post-infection, suggesting a potential breakdown of barrier integrity." (PMID 33113348, 2020). "The level of β-catenin (AJ adaptor protein) and claudin-5 (TJ protein) protein expression appeared normal however their junctional localization appeared disorganized at late stages of infection (arrows)." (PMID 31387911, 2019). "There were significant increases in occludin and claudin-5 expressions in the meninges of the cerebrum and cerebellum in the second and third weeks after infection compared to the controls and those infected for 1 week." (PMID 30845271, 2019). "The expressions of CSF tight junctional proteins claudin-5 and occludin in Western blot analysis tended to be higher 3 weeks after infection compared to the uninfected mice (p = 0.0286 and p = 0.057, respectively)." (PMID 30845271, 2019). "We demonstrate here that one-week of eptifibatide treatment in EcoHIV-infected mice one month post infection, significantly reduced BBB permeability and the associated platelet activation and sC40L levels via normalization of claudin-5 and ZO-1expression." (PMID 26986758, 2016). "At 2 months post-infection expression of claudin-5, a TJ protein known to be highly expressed in brain endothelium, was evaluated." (PMID 26986758, 2016). "This decrease was also observed in brain sections collected from infected mice two months post infection that was analyzed for claudin-5 immunoreactivity." (PMID 26986758, 2016). "After 2 weeks post infection, it was found that, compared to uninfected WT mice, claudin-5 expression was significantly lower in infected WT mice whereas infected CD40L KO mice expressed levels of claudin-5 comparable to the uninfected CD40L KO group." (PMID 26986758, 2016).
infection (continued). "As early as two-weeks post-infection, EcoHIV led to increased permeability of the BBB associated with decreased expression of tight junction protein claudin-5, in CD40L and platelet activation-dependent manner." (PMID 26986758, 2016). "Reduction of claudin-5 implies increased blood-CSF barrier permeability and leukocyte migration across the blood-CSF barrier in choroid plexus after infection with A. cantonensis." (PMID 23505411, 2013). "The blood-CSF barrier permeability assays for the mouse CSF after infection with A. cantonensis showed a significant correlation with the degradation of claudin-5." (PMID 23505411, 2013). "Of the other Claudins assayed, Cldn5 also demonstrated significant changes in transcription levels over the course of infection in all three strains with initial decreases of between 1.6 and 2.7 fold (between days 0 and 7; p≤0.009)." (PMID 20844758, 2010). "Log2 relative expression levels of Cldn13 averaged across all three strains prior to infection are 9.12 (absolute value 770), compared to 7.41 (absolute value 170) of Cldn5 (p = 0.0009), the second most abundant Claudin in spleen." (PMID 20844758, 2010). "While in the control monolayers, both tight junction proteins were properly co-localised in the tight junction domain with a yellow merge impression, we observed that infection with A. cryaerophilus strain 3136 led to a clear reduction in the immunofluorescence signal of claudin-5." (PMID 40545545, 2025). "A downregulation of the barrier forming CLDN5 from the first infection could indicate a disruption in the structure and permeability of TJs allowing C. hepaticus translocation into the liver and bile." (PMID 40446677, 2025). "In contrast, the TJ protein claudin-5 decreases progressively as the infection advances." (PMID 39768195, 2024). "Moreover, immunofluorescence analysis was performed to examine the distribution and expression of ZO-1, Occludin, and Claudin-5 in Egr-1−/− and WT hBMEC upon infection." (PMID 38233877, 2024). "Further, claudin-5, a tight junction protein involved in vascular permeability, and VE-cadherin (vascular endothelial cadherin), a major determinant of endothelial contact that also determines vascular permeability, decreased with infection." (PMID 36952548, 2023). "At 5 d PI, images revealed large areas of the infected iBEC monolayer with low or undetectable Occludin, Claudin-5, and ZO-1, despite a monolayer of adherent cells still present, indicating that the breakdown of TJs occurs with infection, potentially contributing to leakiness of the barrier." (PMID 37139492, 2023). "Interestingly, expression of TJP1, F11R, OCLN and CLDN5 were transiently increased after 2 or 4 days of infection before their downregulation (median increase up to 28.4% for TJP1, 33.5% for F11R, 110.4% for OCLN and 51.6% for CLDN5)." (PMID 37537664, 2023). "To determine if barrier properties might be altered following infection, we immunostained infected iBECs 72 h PI to detect TJ proteins Occludin, Claudin-5, and ZO-1." (PMID 37139492, 2023). "However, ZIKV-PR and ZIKV-U significantly downregulate the expression of ZO-1, OCLN, and CLDN-5 and penetrated the brain parenchyma early after infection." (PMID 36297257, 2022). "Also important in immune cell recruitment, selectins (Selp, Sele) and adhesion molecules (Vcam1) were significantly upregulated in BECs with infection, while tight junction molecules like Cldn5 were downregulated." (PMID 35789215, 2022). "Moreover, in this intranasal infection model, increased mRNA levels of Cdh1 (E-cadherin), Tjp1 (ZO-1), Cldn4 (claudin 4), Cldn5 (claudin 5), and Cldn18 (claudin 18) were observed after IFN-β treatment." (PMID 36559113, 2022). "ZO-1, claudin-5, and occludin decreased at the transcript and/ or protein level of brain endothelial cells after Group B Streptococcus, Neisseria meningitidis, Streptococcus suis, or E. coli infection." (PMID 34437417, 2021).